AGT (angiotensinogen)
Description:
Essential component of the renin-angiotensin system (RAS), a potent regulator of blood pressure, body fluid and electrolyte homeostasis. [Angiotensin-2]: Acts directly on vascular smooth muscle as a potent vasoconstrictor, affects cardiac contractility and heart rate through its action on the sympathetic nervous system, and alters renal sodium and water absorption through its ability to stimulate the zona glomerulosa cells of the adrenal cortex to synthesize and secrete aldosterone. Acts by binding to angiotensin receptors AGTR1 and AGTR2. Also binds the DEAR/FBXW7-AS1 receptor (By similarity). [Angiotensin-3]: Stimulates aldosterone release. [Angiotensin 1-7]: Is a ligand for the G protein-coupled receptor MAS1 (By similarity). Has vasodilator and antidiuretic effects. Has an antithrombotic effect that involves MAS1-mediated release of nitric oxide from platelets (By similarity).
Synonyms: SERPINA8; ANHU; hFLT1
Tractability: Small molecule: it has a binding pocket of medium quality. Antibody: UniProt places it where antibodies can reach, with high confidence; its Gene Ontology location is reachable by antibodies, with high confidence; UniProt predicts a signal peptide or a membrane-spanning region. PROTAC: ubiquitination databases record sites on it; a small molecule that binds it is known. Other modalities: a drug acting on it is in phase 2 or 3 trials.
Target class: Secreted protein
Safety:
Unwanted effects reported when the protein is acted on. In parentheses: how it was acted on, where the effect was seen, and who reports it.
acute coronary syndrome (source: ClinPGx)
Peptic Ulcer Hemorrhage (source: ClinPGx)
Gene: Protein-coding gene on chromosome 1 (230,690,776 to 230,745,576, reverse strand). Ensembl gene ENSG00000135744.
Subcellular location: Secreted
Pathways (Reactome):
Signal Transduction: G alpha (i) signalling events; G alpha (q) signalling events; Peptide ligand-binding receptors
Metabolism: PPARA activates gene expression
Metabolism of proteins: Metabolism of Angiotensinogen to Angiotensins
Gene Ontology:
Molecular function: growth factor activity; hormone activity; protein binding; type 1 angiotensin receptor binding; type 2 angiotensin receptor binding; serine-type endopeptidase inhibitor activity
Biological process: angiotensin-activated signaling pathway; G protein-coupled receptor signaling pathway; kidney development; maintenance of blood vessel diameter homeostasis by renin-angiotensin; negative regulation of MAP kinase activity; negative regulation of neurotrophin TRK receptor signaling pathway; positive regulation of branching involved in ureteric bud morphogenesis; positive regulation of cholesterol metabolic process; positive regulation of cytokine production; positive regulation of DNA-templated transcription; positive regulation of endothelial cell migration; positive regulation of epidermal growth factor receptor signaling pathway; positive regulation of extracellular matrix assembly; positive regulation of extrinsic apoptotic signaling pathway; positive regulation of gap junction assembly; positive regulation of inflammatory response; positive regulation of macrophage derived foam cell differentiation; positive regulation of miRNA transcription; positive regulation of phosphatidylinositol 3-kinase/protein kinase B signal transduction; positive regulation of reactive oxygen species metabolic process; regulation of blood pressure; regulation of cardiac conduction; regulation of extracellular matrix assembly; renal system process; response to angiotensin; and 19 more
Cellular component: blood microparticle; extracellular exosome; extracellular matrix; extracellular region
Genetic constraint (gnomAD): Loss-of-function variants: 26 observed, 30.02 expected, observed/expected ratio (o/e) 0.87, 90% interval 0.63 to 1.2. The upper end of that interval is the gene's LOEUF score, 1.2, which puts it in group 5 of 6, group 1 being the genes least tolerant of losing a copy. Missense variants: 596 observed, 624.45 expected, observed/expected ratio (o/e) 0.95, 90% interval 0.89 to 1.02. Synonymous variants: 259 observed, 274.89 expected, observed/expected ratio (o/e) 0.94, 90% interval 0.85 to 1.04.
Homologues: Orthologues: chimpanzee AGT (99% identical), macaque AGT (92% identical), rabbit AGT (68% identical), pig AGT (67% identical), dog AGT (67% identical), guinea pig AGT (64% identical), rat Agt (64% identical), mouse Agt (61% identical), tropical clawed frog agt (30% identical), zebrafish agt (25% identical). Paralogues in human: SERPINF2 (21% identical), SERPINA3 (20% identical), SERPINA5 (20% identical), SERPINA9 (20% identical), SERPINA1 (20% identical), SERPINA11 (19% identical), SERPINA12 (19% identical), SERPINF1 (19% identical), SERPING1 (19% identical), SERPINA6 (18% identical), SERPINA7 (18% identical), SERPINA10 (18% identical), and 24 more.
Diseases named in the same sentence as AGT in open-access papers:
AGT is named in the same sentence as 677 diseases in open-access papers, as found by Europe PMC text mining. Sharing a sentence is not in itself a finding about the gene and the disease. The quoted sentences say what the papers report.
Hypertension (3,485 papers, 1993 to 2026). The presence of chronic increased pressure in the systemic arterial system. "In this study, we found a significant association between the AGT M235T polymorphism and increased risk of hypertensive IHD." (PMID 40717713, 2025). "Elevated AGT levels are associated with hypertension, inflammation, kidney injury, cell migration, and fibrosis, all of which are critical steps in kidney disease progression." (PMID 41154628, 2025). "Taken together, these factors contribute to placental redox stress that activates the modulating disulphide of angiotensinogen and hence underlies the development of the hypertension of pre-eclampsia." (PMID 40699774, 2025). "AGT SNPs (T174M and M235T) are among the most prevalent variants that cause hypertension in several populations." (PMID 40640196, 2025). "Renin converts angiotensinogen to angiotensin I, and angiotensin-converting enzyme (ACE) metabolizes angiotensin I to angiotensin II, which causes high blood pressure and leads to myocardial hypertrophy and fibrosis." (PMID 41426862, 2025). "AGT plays a critical role in maintaining fluid and electrolyte homeostasis and has been implicated in the pathogenesis of essential hypertension." (PMID 40564071, 2025). "The present study represents the first genetic report to investigate the AGT gene polymorphisms with hypertension in an isiXhosa-speaking South African population." (PMID 38706806, 2024). "Two genes were associated with the development of hypertension in the Han Chinese population, namely, AGT (rs3789678) and ACE (rs4305) [83••]." (PMID 38411777, 2024). "Single nucleotide polymorphisms (SNPs) in the angiotensinogen (AGT) gene are reported to have a significant association with hypertension; however, there are limited studies done on South African populations." (PMID 38706806, 2024). "Accordingly, this study aims to investigate the association between the AGT M235T polymorphism and essential hypertension within the Jordanian population." (PMID 38541014, 2024). "In conclusion, our study at the University of Jordan Hospital investigated the association between the AGT M235T polymorphism and essential hypertension in Jordan." (PMID 38541014, 2024). "Further clinical studies are needed to confirm the association of AGT M235T with the essential hypertension through a multi-central and multi-ethnic study." (PMID 38541014, 2024). "A recent study highlighted the involvement of AGT (rs699) in insulin sensitivity, while AGT rs4762 and rs699 have shown significant associations with hypertension in several ethnic populations." (PMID 37693342, 2023). "The M235T polymorphism is localized in the AGT gene, which results in a threonine to methionine change at position 235 and is associated with hypertension." (PMID 36845669, 2023). "We included the variables with a P value ≤ 0.05 such as eNOS Glu298Asp, ACE I/D, and AGT M235T polymorphisms and traditional risk factors, and we used hypertension as the dependent variable." (PMID 36845669, 2023). "Clinical studies had identified that M235T polymorphism in the angiotensinogen gene was associated with higher risk for hypertension." (PMID 36845669, 2023). "Among all the identified polymorphisms of AGT, M235T, and T174M variants, showed the most significant association with hypertension in various in different populations." (PMID 37201134, 2023). "Various polymorphic forms of AGT have been identified, demonstrating evidence of association with hypertension and certain CVDs." (PMID 37693342, 2023). "The M235T polymorphism, a polymorphism of the AGT gene, has been shown to be associated with increased plasma angiotensinogen levels and increased risk for hypertension, including resistant hypertension." (PMID 37416924, 2023). "A case-control study in China involving 538 individuals demonstrated a positive association between hypertension and AGT T174M (rs4762) genetic polymorphism." (PMID 37693342, 2023).
Hypertension (continued). "In conclusion, this study examined the association between AGT T174M (rs4762) genetic polymorphism and hypertension, particularly in the presence of DM." (PMID 37693342, 2023). "Specifically, M235T allele of the angiotensinogen gene was linked to an increased risk of hypertension in two separate studies involving 27, 906 individuals." (PMID 36329155, 2023). "Hypertension is strongly correlated with the T allele of M235T, which is related to greater plasma AGT." (PMID 36557328, 2022). "Several studies have identified differentially methylated positions (DMPs) located in RAAS-related genes to be associated with hypertension, including the AGT, AGTR1, ACE, NOS3, and SCNN1A genes." (PMID 36457109, 2022). "AGT M235T is seen to be associated with hypertension, pre-eclampsia, diabetic nephropathy, obesity, depression, and various cardiovascular diseases." (PMID 36557328, 2022). "Increased angiotensinogen (AGT) production by white adipose tissue has been related to both obesity and hypertension, and loss of Agtr2 expression is sufficient to rescue obesity induced by adipose tissue AGT overexpression." (PMID 35208177, 2022). "AGT T174M and AGT M235T are one of the most common variants responsible for hypertension in several populations." (PMID 36557328, 2022). "The single nucleotide polymorphisms of AGT T174M (rs4762) and AGT G-6A (rs5051) have been linked to hypertension in Europe and Asia." (PMID 36557328, 2022). "AGT rs4762 has been associated with early onset of hypertension and increased systolic blood pressure (SBP) in the Hutterian Brethren and Japanese populations." (PMID 36557328, 2022). "As RAS has been involved in cardiovascular physiology and pathology, AGT polymorphisms often confer susceptibility to cardiovascular diseases such as hypertension and myocardial infarction." (PMID 35213964, 2022). "Another study has also shown a significant association of AGT M235T and AGT T174M polymorphism with essential hypertension in females as compared to males among the Indian population." (PMID 36557328, 2022). "Various case–control studies showed a significant association of AGT M235T polymorphism with essential hypertension in females as compared to that in males among the South Indian population." (PMID 36557328, 2022). "Coexistence of T2DM and hypertension can also be explained genetically, since there is evidence indicating that variants of angiotensinogen and adrenomedullin gene are associated with both conditions." (PMID 33021758, 2021). "The realization that each of these anchors can be readily modified by external influences emphasizes the modulatory role of angiotensinogen and opens new prospects for the investigation of the causes and ultimately the treatment of hypertension." (PMID 33816576, 2021). "In this study, AGT M235T, duration of hypertension, BMI, and EF were found to be associated with calculated LVMI in Vietnamese patients diagnosed with essential hypertension." (PMID 33681303, 2021). "Our data showed that DMB protected hypertension is associated with the restoration of expression of AGT and ACE induced by TCDD." (PMID 34578924, 2021). "Previously reported that the C allele (threonine variant) of AGT rs699 is associated with increased plasma angiotensinogen and hypertension." (PMID 34805533, 2021). "The risk allele of rs5050 preferentially binds USF2, augments angiotensinogen transcription, and is associated with hypertension." (PMID 33919522, 2021). "Association between AGT P.m.ET235THr gene polymorphism and cardiovascular disease concluded that there was a positive correlation between essential hypertension and myocardial infarction." (PMID 34150864, 2021). "AGT, another gene with a highly differentiated SNP, rs699, with a derived allele frequency of 17% in Africans, has also been associated with hypertension in African populations." (PMID 32171244, 2020).
Hypertension (continued). "Based on the single-tissue eQTL in GTEx, the NUCB2 rs757081 and AGT rs699 decreases their gene expression levels in several tissues and both SNPs have been associated with hypertension in the GWAS catalogue." (PMID 32171244, 2020). "Deregulation of AGT which is a crucial component of the RAS pathway is associated with the pathogenesis of essential hypertension and atrial fibrillation." (PMID 33233425, 2020). "AGT is an important regulator of blood pressure, and SNPs in the AGT gene are associated with increases in serum AGT levels and hypertension." (PMID 30700972, 2019). "Changes in oxidative stress parameters in COPD-only patients and patients with comorbid COPD and hypertension depending on polymorphisms in the AGT gene (Me [Lq; Uq])." (PMID 32025262, 2019). "In another study, a single variant that converts methionine to threonine at amino acid 235 (M235T) of the angiotensinogen gene (AGT) was found to be associated with hypertension in Caucasians." (PMID 30832344, 2019). "Most intriguingly, it was found that an increased ratio of oxidized AGT over the reduced form in plasma is associated with preeclampsia, a hypertensive disease during pregnancy." (PMID 30563843, 2019). "For example, a mild increase (10–20%) in plasma concentrations of human AGT caused by the M235T polymorphism is often associated with essential hypertension." (PMID 30563843, 2019). "Hereby, we explore the interaction of ACE and AGT gene polymorphisms with known risk factors such as hypertension for the development of DR in Chinese T1DM patients." (PMID 29484134, 2018). "The AGT gene and its genetic variants have been previously studied in the context of the pathogenic mechanisms of essential hypertension, particularly the impact of plasma AGT levels on blood pressure." (PMID 30383794, 2018). "The results of the present study confirmed and reestablished the role of AGT gene variants and their haplotypes in the causation of hypertension in Indian population and showed that haplotypes can provide stronger evidence of association." (PMID 28361007, 2017). "An increased risk of hypertension has been associated with angiotensinogen (AGT), angiotensin-converting enzyme (ACE), and angiotensin II receptor 1 (AGTR1)." (PMID 28903744, 2017). "Hypertension is one such risk phenotype of cardiovascular disorders putatively associated with AGT variants." (PMID 28361007, 2017). "The M235 T (methionine substituted by threonine) polymorphism in the AGT gene was associated with hypertension in Caucasians and with a 10–20% increase in plasma angiotensinogen levels in individuals homozygous for the T allele." (PMID 28903744, 2017). "Further studies will investigate the function of intrarenal Smyd3 in the regulation of intrarenal AGT expression and the development of hypertension and RAS associated kidney injury." (PMID 28572913, 2017). "Haplotype analysis showed a significant association between AGT rs4762 and rs699 with hypertension among Caucasian and Taiwan Chinese populations." (PMID 28828324, 2017). "Further, to the best of our knowledge this is the first report of association of individual SNPs and haplotype blocks of AGT with hypertension in an Eastern Indian population." (PMID 28361007, 2017). "Our previous study found that the ancestral types (risk allele) of polymorphisms in the hypertension susceptibility AGT gene were prevalent in the populations of the Solomon Islands and its rs5049 polymorphism was associated with hypertension." (PMID 28253292, 2017). "Although human angiotensinogen (hAGT) gene is associated with hypertension, its transcriptional regulation in pathological scenarios like obesity is poorly understood." (PMID 28467442, 2017). "Haplotype analyses of the AGT gene and its association with hypertension have also been reported in whites and Japanese." (PMID 28361007, 2017).